GRK2 (G protein-coupled receptor kinase 2)
Diseases named in the same sentence as GRK2 in open-access papers (continued):
Sharing a sentence is not in itself a finding about the gene and the disease.
cardiac hypertrophy (continued). "In order to determine if obesity-induced cardiac remodeling could be affected by GRK2 dosage we set out to study the hearts of mice fed for 30 weeks with HFD, since 12 weeks were not enough to induce cardiac hypertrophy (data not shown)." (PMID 27832814, 2016). "However, involvement of GRK2 in GPCR and non-GPCR signaling may also indicate direct modulation of molecular pathways involved in the regulation of cardiac hypertrophy." (PMID 28759639, 2017).
Sepsis (22 papers, 2012 to 2024). Sepsis is defined as life-threatening organ dysfunction caused by a dysregulated host response to infection. "In malaria and sepsis, neutrophils showed an increased expression of GRK2 levels associated with decreased CXCR2 expression and reduced responses to IL-8." (PMID 33806057, 2021). "Another study that analyzed samples of sepsis patients showed low GRK2 mRNA expression, a finding that was indirectly associated with a reduction in granulocyte migration." (PMID 33111742, 2020). "In experimental mouse models of sepsis, GRK2 upregulation in neutrophils was associated with the decreased expression of CXCR2 at the cell surface and a subsequent decrease in the migration of neutrophils to infection sites, resulting in shorter survival of the mice." (PMID 33466410, 2021). "In conclusion, a NO‐dependent reduction in GRK2 level in the kidney of Sepsis plays a role in S‐AKI by interacting with α1 adrenergic receptors." (PMID 39438268, 2024). "Corroborating these findings, a recent study showed that renal vascular reactivity to alpha-1-adrenergic agonist is preserved in sepsis due to the NO-dependent G protein-coupled receptor kinase 2 (GRK2) reduction in the kidneys from septic mice." (PMID 35722824, 2022). "CXCR2 downregulation in sepsis depends on its phosphorylation by the G protein-coupled receptor kinase-2 (GRK2) and the upregulation of a serin-threonine protein kinase." (PMID 36451225, 2022). "For example, the blockade of PI3K restored CXCR2 surface levels on neutrophils via inhibition of GRK2 in a septic mouse model and translated into a better prognosis of sepsis." (PMID 36451225, 2022). "Conversely, sepsis-associated inflammation is reduced in GRK5-deficient mice, suggesting opposite effects of GRK2 and GRK5 on myeloid cells and/or effects in other cell types." (PMID 33466410, 2021). "GRK2 is upregulated in sepsis, HF, BD and post-ischemia, and translocation of GRK2 to the mitochondria can influence fatty acid oxidation and ATP production rate." (PMID 31387264, 2019). "GRK2 and GRK5 expression are enhanced in sepsis patients and in rodent models of severe sepsis, which are associated with impaired migration of neutrophils and enhanced susceptibility to secondary microbial infection." (PMID 22745844, 2012). "To investigate whether Mincle regulates GRK2 expression in CLP sepsis, we quantitatively examined GRK2 expression." (PMID 28112221, 2017). "This response is hampered in sepsis where endotoxin upregulates G-protein-coupled receptor kinase 2 (GRK2) reducing cell surface expression of chemotactic receptors on the neutrophil plasma membrane resulting in inefficient neutrophil activation and recruitment." (PMID 24357647, 2014). "Both FPR1 and CXCR2 have been shown to be downregulated by induction of GRK2 in sepsis." (PMID 24755316, 2014). "Therefore, Mincle could reduce GRK2 expression in sepsis both directly and indirectly by downregulating TLR4 signaling." (PMID 28112221, 2017). "It was shown that GRK2 and GRK5 play a notable role in the pathogenesis of human sepsis by regulating neutrophil chemotaxis, and modulate the outcomes of septic shock via the NF-κB1p105-TPL2-MEK-ERK pathway." (PMID 33806057, 2021). "Molecules known to participate in the mechanism of neutrophil migration, such as GRK2 and CXCR2, were shown to be increased and decreased, respectively, in neutrophils obtained from experimentally-induced sepsis by cecal ligation and puncture (CLP)." (PMID 33111742, 2020). "In a study of sepsis, IL-33 can reverse the decreased expression of CXCR2 in neutrophils through the inhibition of GRK2." (PMID 27721573, 2016). "IL-33 has beneficial effects in experimental sepsis, enhancing the accumulation of neutrophils through the upregulation of CXCR2 via GRK2-dependent pathways at the site of infection and reducing the inflammatory response in systemic sites." (PMID 25614712, 2014).
Sepsis (continued). "Our results suggest that Mincle-mediated GRK2 regulation plays an important role in maintaining high expression of CXCR2 and improving neutrophil infiltration, thus reducing the mortality rate of sepsis." (PMID 28112221, 2017). "In summary, our study demonstrates that exogenous CO inhibits sepsis-induced neutrophil infiltration by interfering with FPR1 via p38 MAPK but not GRK2." (PMID 27144520, 2016). "In addition, NOS‐2 selective inhibitor increased GRK2 levels in the septic kidney, and GRK2 levels of NOS‐2‐KO mice were not reduced during sepsis, thus confirming that NO was indeed involved in the kidney GRK2 disappearance." (PMID 39438268, 2024). "The in vivo and in vitro data support a therapeutic role of CORM-2 in sepsis by interfering with excessive neutrophil infiltration in liver and lung via a p38 MAPK, but not GRK2, pathway." (PMID 27144520, 2016).
Obesity (16 papers, 2010 to 2026). Accumulation of substantial excess body fat. "Using a novel inducible β-cell-specific GRK2 knockout mouse model (βGRK2KO), we establish that loss of adult β-cell GRK2 delays metabolic islet maladaptation, protecting the heart against obesity-induced cardiac dysfunction." (PMID 40054692, 2025). "A very recent study also reveals that mice partially deficient for GRK2 are resistant to the development of NASH independently of obesity and IR." (PMID 30837878, 2019). "Taken together, these findings highlight the therapeutic potential of targeting hepatic GRK2 as a means to correct metabolic abnormalities and protect vascular health in obesity-related CVDs." (PMID 41602450, 2026). "Of note, previous reports have demonstrated that the level of GRK2 in different tissues is increased in situations of obesity and IR." (PMID 33658023, 2021). "Blocking infiltration of macrophages and T lymphocytes in PVAT prevented obesity-induced ED in mice with G protein-coupled receptor kinase 2 (GRK2) deletion in myeloid cells, suggesting GRK2 as a potential therapeutic target." (PMID 34277732, 2021). "Altogether, these results suggest that low levels of GRK2 in myeloid cells can keep at bay the pro-inflammatory reprogramming taking place in different adipose depots during diet-induced obesity." (PMID 33020373, 2020). "Strikingly, the pattern of modulation of GRK2 levels observed in young females during diet-induced obesity situations is lost in middle-aged female animals, which are no longer protected from HFD-induced metabolic disarrays." (PMID 31752326, 2019). "We find that adult GRK2+/− mice gain less weight after a long period (30 weeks) of HFD feeding building on our own data describing similar effects after a 12 weeks-long HFD-induced obesity, and also when GRK2 was depleted in the middle of the HFD period." (PMID 27832814, 2016). "In this work we present evidence that unmasks a protective role of low GRK2 levels on the effects of obesity-induced cardiac remodeling." (PMID 27832814, 2016). "We find that GRK2+/− mice are protected from obesity-promoted cardiac and cardiomyocyte hypertrophy and fibrosis." (PMID 27832814, 2016). "In sum, we can conclude that low levels of GRK2 prevent the development of obesity-induced cardiomyocyte and heart pathological hypertrophy, and also of cardiac fibrosis after a long-term HFD feeding." (PMID 27832814, 2016). "We also report here that GRK2+/− animals appear to be protected from pathological cardiac remodeling induced by obesity." (PMID 27832814, 2016). "In summary, our results point to a protective role of low levels of GRK2 upon obesity-induced cardiac remodeling and steatosis." (PMID 27832814, 2016). "Given that several DPP4i and GLP-1RA have been approved or in clinical development for diabetes and other obesity-related metabolic complications, in future studies it will be important to confirm that selective pharmacological inhibition of GRK2 mediates the overall actions of GLP-1." (PMID 34054727, 2021). "Upregulated GRK2 (with age or as a consequence of comorbidities as obesity) could desensitize the GPER estrogen receptor as has already been suggested, through its canonical actions on GPCRs." (PMID 33803070, 2021). "Our results suggest that myeloid GRK2 could be a potential therapeutic target in the development of endothelial dysfunction induced by PVAT in the context of obesity." (PMID 33020373, 2020). "Given the key role of macrophages in obesity-related vascular complications, we hypothesized that changes in GRK2 levels in myeloid cells may alter the inflammatory pattern of PVAT and thus impact the development of diet-induced vascular dysfunction." (PMID 33020373, 2020). "Therefore, targeting GRK2 by different strategies emerges as a potentially relevant approach to treat cardiovascular disease, obesity, type 2 diabetes, or NAFLD, pathological conditions which are frequently interconnected and present as co-morbidities." (PMID 30837878, 2019).
Obesity (continued). "Next, we sought to explore whether the observed differences in body weight and metabolic alterations between young male and female mice could correlate with divergences or sex-specific modulation of GRK2 levels in the context of diet-induced obesity." (PMID 31752326, 2019). "Ob/ob mice transfected with GRK2 siRNA and control siRNA showed marked obesity." (PMID 28814745, 2017). "Notably, the HFD-induced increase in cardiac GRK2 levels appears to be an early event in the development of obesity-induced cardiac alterations, since it is detected after 12 weeks on HFD in WT animals." (PMID 27832814, 2016). "We investigated the effects elicited by GRK2 downregulation in obesity-related cardiac remodeling." (PMID 27832814, 2016). "Thus, although FF did not directly alter vascular GRK2 expression or activity, its suppression of hepatic GRK2 may represent an important mechanism by which FF improves lipid metabolism and secondarily preserves vascular endothelial function in obesity." (PMID 41602450, 2026). "First, from a therapeutical point of view, GRK2-biased β2AR agonists may represent a promising, orally available alternative to current type 2 diabetes and obesity treatments, although it should be noted that evidence of clinical efficacy in patients has not yet been demonstrated." (PMID 40935847, 2025). "To directly address whether GRK2 dosage in myeloid cells might have a role in vascular functionality and damage, we used a HFD-induced obesity model comparing control animals with those with a selective downregulation of GRK2 in this cell lineage (LysM-GRK2+/−)." (PMID 33020373, 2020). "Since decreased levels of GRK2 attenuate the overall obese phenotype, we cannot discard that the protection against obesity-induced cardiac remodeling observed in GRK2+/− mice could be promoted, at least in part, by the effect of GRK2 downregulation in other tissues." (PMID 27832814, 2016). "Interestingly, several cardiovascular diseases as well as obesity and type 2 diabetes-related disorders, clinical conditions often interrelated as co-morbidities, converge in displaying increased GRK2 levels, pointing at the inhibition of GRK2 as an attractive therapeutic target." (PMID 30837878, 2019). "Strategies aimed at modulating hepatic GRK2 activity and restoring the LKB1/AMPK/Akt/eNOS pathway may provide novel opportunities to ameliorate endothelial dysfunction in obesity-related cardiometabolic diseases." (PMID 41602450, 2026). "Lowering myeloid GRK2 protein could prevent this vicious cycle from establishing and thus stop vascular dysfunction by preventing, on the one hand, the pro-inflammatory shift and, on the other, the increased NADPH oxidase expression observed during obesity." (PMID 33020373, 2020).
Arthritis (15 papers, 2016 to 2025). Inflammation of a joint. "Of note, no changes of GRK2 mRNA levels were observed either in PBMCs of RA patients or in rat splenocytes during adjuvant arthritis, suggesting that the observed down-regulation of GRK2 associated with arthritis involves a process of posttranscriptional modification and/or protein degradation." (PMID 33546162, 2021). "Elevated GRK2 and decreased β2-AR expression were observed in the dendritic cells (DCs) of rats with adjuvant-induced arthritis, and suppression of β2-AR signaling may exacerbate arthritis-associated inflammation." (PMID 29930509, 2018). "In this study, we confirmed GRK2 overexpression in the synovium of RA patients and arthritis animal models, demonstrating its co-localization with PDE4D in RA synovium and its regulation of PDE4D expression in FLSs." (PMID 39990667, 2025). "In future investigations, we aim to establish mice with specific knockout of Pde4d or Grk2 in FLSs and induce experimental arthritis models." (PMID 39990667, 2025). "Both genetic deficiency and pharmacological inhibition of GRK2 have remarkably reduced PDE4D expression, consequently ameliorating the severity and progression of arthritis in animal models." (PMID 39990667, 2025). "Collectively, these results demonstrate that Grk2 deficiency reduces PDE4D expression and effectively ameliorates the severity and progression of experimental arthritis." (PMID 39990667, 2025). "Crucially, utilizing Grk2-deficient mice, we showed that endogenous Grk2 knockdown significantly decreased PDE4D expression, alleviating arthritis symptoms in the CAIA model." (PMID 39990667, 2025). "Abundant expression of both PDE4D and GRK2 was observed in synovial tissues from both experimental arthritis animals and RA patients, with synchronized expression noted in RA patients." (PMID 39990667, 2025). "Both genetic deficiency and pharmacological inhibition of GRK2 decreased PDE4D expression, ameliorating arthritis severity in animal models." (PMID 39990667, 2025). "Genetic deletion or pharmacological inhibition of GRK2 significantly attenuated the progression of arthritis in animal models." (PMID 39990667, 2025). "Firstly, it would be more convincing to induce an experimental arthritis model in FLSs-specific Pde4d or Grk2 deletion mice." (PMID 39990667, 2025). "Our work provides a comprehensive understanding of the pathological function of GRK2 in arthritis and confirms that selective GRK2 inhibitors, such as CP-25, are promising and effective antirheumatic drugs." (PMID 38037039, 2023). "This agrees with the reported effects of targeted GRK2 kinase domain inhibition to reverse synoviocyte dysfunction and ameliorate collagen-induced arthritis in a rat model." (PMID 35887281, 2022). "In our arthritis model, we found an increased expression of β-arrestin and GRK2 in chondrocytes, but β2-AR agonist when administered at disease onset throughout the course of study, inhibited β-arrestin and GRK2 expression." (PMID 36188601, 2022). "In a rat model of adjuvant arthritis, GRK2 is also downregulated in splenocytes and mesenteric lymph node cells upon induction of arthritis." (PMID 33546162, 2021). "Inflammatory activity during arthritis alters GRK2 level only in B cells and CD4+ T cells, the cell subsets that drive this disease, but not in CD8+ T cells or in thymocytes." (PMID 33546162, 2021). "Our group has long been committed to the role of GRK2 in RA and arthritis animal models, here we investigated the effect of GRK2 on macrophage polarization in RA for the first time." (PMID 31818003, 2019). "The levels of GRK2 were also decreased in immune cells in the complete Freunds adjuvant animal model of arthritis." (PMID 29922165, 2018). "Western blot data shows that the expression of GRK2 in splenic T cells was obviously increased with the onset of arthritis and was recovered in the remission period, suggesting that GRK2 is involved in the progress of RA." (PMID 28349925, 2017).
Arthritis (continued). "However, inhibiting G protein-coupled receptors (GPCRs) desensitization mediated by G protein coupled receptor kinase 2 (GRK2) led to increased cAMP concentration and relieved experimental arthritis models." (PMID 39990667, 2025). "Our group has long been committed to the role of GRK2 in RA and arthritis animal models." (PMID 37242446, 2023). "Similarly, SBT significantly decreased arthritis- induced upregulation of β-arrestin and GRK2 in murine chondrocytes." (PMID 36188601, 2022). "During arthritis, level of catecholaminergic messengers and density of sympathetic nerve fibers decrease in lymphatic tissues, hence decrease in GRK2 might serve as an early compensatory mechanism for the reduced amounts of catecholamines." (PMID 36009497, 2022). "Moreover, we observed a profound downregulation of GRK-2 shortly after induction of arthritis and an increase in β-Arrestin 2 only at late stage of arthritis." (PMID 36009497, 2022). "Our findings suggest that β2-AR agonists used in the early course of arthritis could inhibit inflammation and prevent receptor desensitization by β-arrestin and GRK2 signaling in chondrocytes." (PMID 36188601, 2022). "The fact that reduction in GRK2 protein level occurs after induction of arthritis in rats and returns to normal levels during disease remission suggests that inflammatory activity could directly alter GRK2 level in immune cells." (PMID 33546162, 2021). "In contrast, Grk2+/- CAIA mice showed a significant reduction in swollen joint counts and arthritis index." (PMID 39990667, 2025). "GRK2 level is reported to be reduced in an animal model of EAE and adjuvant-induced arthritis and some autoimmune diseases like arthritis and multiple sclerosis in humans." (PMID 35492402, 2021). "Consequently, GRK2 may be an important molecular target in arthritis." (PMID 27079168, 2016). "Furthermore, pharmacological inhibition of GRK2 by CP-25 substantially suppressed PDE4D expression and impeded arthritis development in the CIA model." (PMID 39990667, 2025). "Therefore, in the present work, we demonstrated that GRK2-mediated Gαi coupling to β2AR in inflammatory FLSs exacerbates cAMP signalling inhibition and increases FLS proliferation in the setting of arthritis." (PMID 38037039, 2023). "In other words, the low GRK2 levels observed in lymphocytes are believed to be the consequence of the disease process and not a reflection of preexisting low levels of GRK2 in patients with arthritis." (PMID 33546162, 2021).